IL1B (interleukin 1 beta)
Diseases named in the same sentence as IL1B in open-access papers (continued):
Sharing a sentence is not in itself a finding about the gene and the disease.
pulmonary fibrosis (continued). "IL-1β rs16944, IL-18 rs549908 and rs1946519 have been shown to be associated with susceptibility to chronic obstructive pulmonary disease, pulmonary fibrosis, respectively." (PMID 23110140, 2012). "IL-1β overexpression in mice causes pulmonary fibrosis, and more recent work shows that IL-1β enhances bleomycin-induced fibrosis by upregulating IL-17A." (PMID 20738867, 2010). "Amongst them, IL‐1β, IL‐10, and IL‐13 are associated with pulmonary fibrosis." (PMID 38952051, 2024). "Interestingly, the IL1β pathway has been associated with the development of lung fibrosis, stimulating collagen synthesis and the proliferation of fibroblasts and promoting the expression of the pro-fibrosis marker TGFβ1." (PMID 38542124, 2024). "Considering our observations and those of others, PI3K/AKT and MEK/ERK pathways might be a valid target for therapeutic intervention in lung fibrosis associated with IL-1β-mediated EMT." (PMID 39118068, 2024). "IL-1β has been implicated in the deposition of collagen, and the IL-1 receptor antagonist may be able to reduce pulmonary fibrosis provoked by silica and bleomycin." (PMID 26496436, 2015). "Transient overexpression of IL-1β caused acute lung injury resulting in pulmonary fibrosis in rats." (PMID 22322675, 2012). "Furthermore, both IL-1α and IL-1β have been shown to be increased in mice following bleomycin challenge and IL-1α-, IL-1β- and IL-1R1-deficient mice are protected from bleomycin-induced pulmonary fibrosis." (PMID 27001429, 2016). "We were also intrigued by the role of alveolar macrophages in lung fibrosis and were able to demonstrate that in vivo treatment with bleomycin induced an increase in macrophage size and IL-1β release and that both were inhibited with PIPE-791." (PMID 40887574, 2025). "IL-1β, as a pro-inflammatory cytokine, plays a multifaceted role in the formation of pulmonary fibrosis." (PMID 40391214, 2025). "A previous study reported that the fenugreek seed extract reduced IL-6 in an ovariectomized rat model and downregulated NF-κB, TNF-α, IL-6, IL-8, and IL-1β in a pulmonary fibrosis animal model." (PMID 39941027, 2025). "Early research indicates that IL-1β promotes pulmonary fibrosis in vivo by activating IL-1 receptor-dependent signaling pathways." (PMID 40391214, 2025). "Transforming-growth factor beta 1 (TGF-β1) and the pro-inflammatory interleukins Il-1β, IL-4, IL-13, and Il-18 are involved in stimulating the formation of pulmonary fibrosis." (PMID 41597294, 2025). "Then, the activated NF-κB upregulates the expression of NLRP3 and IL-1β again, forming a positive feedback loop that triggers an inflammatory cascade, ultimately leading to pulmonary fibrosis." (PMID 40391214, 2025). "Inhibition of lung injury healing, promotion of lung cell death, and eventual induction of pulmonary fibrosis can be caused by TGF-β1, IL-1β, IL-6, and TNF-α." (PMID 40665395, 2025). "Lastly, we show that PIPE-791 reduces IL-1β release in rodent and human alveolar macrophages, highlighting a possible role for alveolar macrophages in the etiology of lung fibrosis." (PMID 40887574, 2025). "On a similar note, RGC-32 deficiency in mice has been shown to significantly improve skin and lung fibrosis (sclerosis) by inhibiting the expression of inducible NO synthase (iNOS) and IL-1β in macrophages." (PMID 40507709, 2025). "Studies have demonstrated that the activated NLRP3 inflammasome can promote pulmonary EMT via the IL-1β/IL-1Rs/MyD88/NF-κB signaling pathway, leading to pulmonary fibrosis." (PMID 40391214, 2025). "BLM-induced lung injury leads to IL-1β production and pulmonary fibrosis via activation of the NALP3 inflammasome." (PMID 40438789, 2025). "Similar data on the role of the Th17-dependent immune response were obtained for IL-1β-induced pulmonary fibrosis, as well as pulmonary fibrosis induced by the graft-versus-host reaction." (PMID 39201632, 2024).
pulmonary fibrosis (continued). "This study also showed that the expression of MYD88 and IL-1β significantly increased in LPS-induced pulmonary fibrosis, whereas the overexpression of let-7a-5p significantly downregulated the expression of MYD88." (PMID 38875245, 2024). "Unlike the other neuropeptides (CGRP, SP and VIP), NPY is a vasoconstrictor and also promotes angiogenesis and blocked generation of pulmonary fibrosis through inhibition of IL-1β." (PMID 38183438, 2024). "For example, nintedanib treating idiopathic pulmonary fibrosis can reduce the expression of proinflammatory factors IL-1β, IL-6, and TNF-ɑ by downregulating the PI3K/Akt/mTOR pathway." (PMID 39108701, 2024). "In the acute lung injury model, NKS3 decreased lung fibrosis and inflammatory cytokines (IL-1β, IL-6 and TNF-α) and nitric oxide (NO) production in broncho-alveolar lavage fluid." (PMID 38598021, 2024). "It has been reported that the expression of MYD88 and IL-1β is increased in bleomycin-induced pulmonary fibrosis in mice." (PMID 38875245, 2024). "On the other hand, systemic increase of activity of TNF-α and IL-1β, which are markers of M1 macrophages, has been shown to promote myofibroblast differentiation and exacerbate bleomycin-induced pulmonary fibrosis." (PMID 37291088, 2023). "Previous studies in animal models and patients with pulmonary fibrosis have found that IL-1β and IL-18 levels were significantly elevated in BALF and BALF macrophages, consistent with pre-existing NLRP3 inflammasome activation." (PMID 38136142, 2023). "Consistent with the earlier studies, we found that overexpression of Sestrin2-inhibited ROS production and the level of TNF-α, IL-6, and IL-1β to attenuate endoplasmic reticulum stress and ferroptosis, thereby ameliorating lung fibrosis." (PMID 38023615, 2023). "In particular, during the initial phases of the fibrotic process, NF-κB increases the expression of genes coding for the synthesis of many inflammatory cytokines, such as TNFα, IL6, IL1β and TGFβ, essential for the development of pulmonary fibrosis." (PMID 37626373, 2023). "Next, we tested the efficacy of neutralizing IL-1β in influenza-infected aged mice and observed dramatic attenuation of lung fibrosis, which phenocopies the results of CD8+ T cell depletion, and neutralization of IFN-γ and TNF." (PMID 38077031, 2023). "This benefit in the lung function is supported indirectly by the measurements of IL-1β and of IL-1ra (receptor antagonist) in the epithelial lining fluid of 54 patients with idiopathic pulmonary fibrosis (IPF)." (PMID 37680472, 2023). "The enzyme-linked immunosorbent assay (ELISA) of the whole lung extracts showed that IL-1β levels were significantly higher in the pulmonary fibrosis model group compared to the control group seven days after bleomycin injection." (PMID 37958797, 2023). "SARS-CoV-2-infected NHBE cells exhibited a significant increase in lung fibrosis-related genes (e.g., IL1B)." (PMID 37521843, 2022). "An increase in total cell numbers and enrichment of inflammatory cytokines (TNF-α and IL-1β) in BALF are the hallmarks of BLM—induced pulmonary fibrosis." (PMID 35628193, 2022). "The release of proinflammatory cytokines like TNF-α, IL-1β, and IL-6 in the lung tissue microenvironment by stimulated macrophages and fibroblasts contributes to the persistence of lung fibrosis by activating fibroblasts in an autocrine/paracrine fashion." (PMID 35377906, 2022). "The transcription of many inflammatory cytokines, such as TNFα, IL6, IL1β and TGFβ, are vital in development of lung fibrosis." (PMID 35083615, 2022). "MIR3142HG, the host gene for miR-3142 and miR-146a, was reported to regulate the IL-1β-induced inflammatory response in idiopathic pulmonary fibrosis (IPF) and to be highly expressed in LPS-exposed human pulmonary microvascular endothelial cells (HPMECs)." (PMID 36575377, 2022).
pulmonary fibrosis (continued). "Although fibroblasts activation and differentiation played a pivot role in lung fibrogenesis, inflammatory mediators such as TNF and IL-1β have an important effect on the initiation and development of lung fibrosis." (PMID 35548340, 2022). "In bleomycin-induced lung fibrosis, genetic ablation of BAFF or BAFF neutralization by a soluble receptor significantly attenuates pulmonary fibrosis and IL-1β levels." (PMID 36590969, 2022). "Together with reactive oxygen species, IL-6, IL-8, IL-1β, GM-CSF, and other chemokines cause ARDS, leading to pulmonary fibrosis and death." (PMID 34463916, 2022). "In vivo experiments have shown that IL-1β induces progressive pulmonary fibrosis through long-term activation of TGF-β signaling." (PMID 36733806, 2022). "Previous studies have demonstrated that significantly increased expressions of IL-1β, IL-8 and IL-6 in bronchoalveolar lavage fluid from patients with pulmonary fibrosis in comparison with controls." (PMID 34742261, 2021). "Some studies have also shown that over-expression of either TNFα or IL-1β in mouse lungs leads to spontaneous pulmonary fibrosis." (PMID 33999928, 2021). "In a model of bleomycin-induced pulmonary fibrosis, pHD decreased the level of tissue IL-1β and TGF-β, prevented the infiltration of the lung parenchyma by CD16+ cells, and reduced perivascular and peribronchial inflammation." (PMID 34070506, 2021). "After adjustment for age, the PMN %, TNF-α, IL-1B, SDF-1α, MMP1, and calprotectin were associated with lung fibrosis (kurtosis and skewness) and density (HAA)." (PMID 34682263, 2021). "Among the overexpressed cytokine present in cytokine storms is interleukin-1 beta (IL-1β), which is also implied in the pathogenesis of pulmonary fibrosis." (PMID 34306796, 2021). "Immune cells of BALF of patients with idiopathic pulmonary fibrosis (IPF) showed an increased production of IL-1β and hyper-inducible NLRP3 activation." (PMID 34445540, 2021). "The inflammatory molecule tumor necrosis factor α (TNFα) has been shown to activate latent TGFβ while overexpression of interleukin 1β (IL-1β) sustains TGFβ expression and promotes lung fibrosis." (PMID 34011367, 2021). "The exact mechanisms implicating DAMPs in fibrosis are currently incompletely elucidated but include direct interactions with fibroblasts as well as epithelial cells and promotion of IL-1β production, a cytokine involved in lung fibrosis." (PMID 34093523, 2021). "For example, the favorable group for pulmonary fibrosis includes IL-1β, IL-4, IL-6, IL11, IL-13, IL-17A, IL-15, and IL-33; in contrast, the other group with anti-fibrotic function has IL-7, IL-10, IL-12, and IL-27." (PMID 35082682, 2021). "The microbial burden was however associated with baseline IL-1β release as well as AIM2 and IL-18 mRNA expression in lung fibrosis." (PMID 34220810, 2021). "The profibrotic role of IL-1β has long been known: mice overexpressing IL-1β have an exacerbated response to bleomycin-induced lung fibrosis." (PMID 34258628, 2021). "After isolation of mouse primary lung fibroblasts, BLM was added to the mouse primary lung fibroblasts, and it was found that NLRP3 inflammasome regulate IL-1β via miR-155, leading to lung fibrosis." (PMID 34177893, 2021). "Various investigations have revealed that Thal prevents bleomycin- or paraquat-induced pulmonary fibrosis in murine models by downregulating the expression of IL-6, IL-8, IL-1β, TNF- α, TGF-β, collagen, hydroxyproline, VEGF, p-JNK and α-SMA." (PMID 35126133, 2021). "In this study we demonstrated that AMs in pulmonary fibrosis secrete abundantly IL-1β following stimulation of the NLRP3 and AIM2 inflammasomes compared to healthy subjects." (PMID 34220810, 2021). "NLRP3 inflammasome lead to pulmonary fibrosis through the IL-1β/IL-1Rs/MyD88/NF-κB signaling pathway." (PMID 34177893, 2021). "In the process of pulmonary fibrosis, IL-1β stimulates the proliferation of fibroblasts and the production of type I and III collagen." (PMID 34054346, 2021).
pulmonary fibrosis (continued). "Both IL-1β and IL-8 have been characterized as key contributors to the pathogenesis of many inflammatory lung diseases, including the bronchiectasis, pulmonary fibrosis, acute respiratory distress syndrome, chronic obstructive pulmonary disease and asthma." (PMID 34083710, 2021). "IL-1β not only induces alveolar inflammation but also pulmonary interstitial fibrosis through the excessive repair of local injury." (PMID 33817248, 2020). "For example, lung fibrosis-associated genes (CSF3, IL8, CSF2, IL6, TNF, MMP9, IL1B and PDGFB) were significantly upregulated in SARS-CoV-2-infected NHBE cells." (PMID 32698440, 2020). "Activation of p38 MAPK signaling pathway in pulmonary macrophages promotes lung fibrosis through secretion of IL-6, IL-1β, and TNF-α, all of which are the direct targets of p38 MAPK pathway." (PMID 32271749, 2020). "The relevance of inflammasome activation and IL-1β signaling in fibrotic parenchyma remodeling has been shown for silica induced- ILDs, bleomycin-induced lung fibrosis and various other organ systems." (PMID 32431623, 2020). "For example, serum levels of IL-1β in idiopathic pulmonary fibrosis patients were significantly increased compared to healthy controls, as well as in BALF." (PMID 33330522, 2020). "DHP mainly regulated pulmonary fibrosis-related inflammatory genes and signaling pathways, such as IL1β, IL4, IL5, IL6, TGFβ1, and TNFα." (PMID 31105564, 2019). "Among them, IL-1β is a proinflammatory regulatory factor involved in the regulation of inflammation and fibrosis, which is crucial in the early stage of pulmonary fibrosis." (PMID 30147727, 2018). "IL-1β can drive the progression of pulmonary fibrosis, and it is known to mediate the release of other inflammatory cytokines such as TNF-α and IL-6." (PMID 30087305, 2018). "In the pathogenesis of pulmonary fibrosis, expression and secretion of pro-inflammatory and pro-fibrotic mediators such as IL-1β, TNFα and TGF-β1 play a crucial role." (PMID 30510259, 2018). "miRNA-155 (miR-155) plays a role in pulmonary fibrosis and its expression can be induced with interleukin (IL)-1β." (PMID 28623945, 2017). "Different studies suggest that IL-1β, IL-6, IL-8, MIP-1α, LTB4, and TGF-β1 levels are associated with subsequent BPD development and promote lung fibrosis." (PMID 29209598, 2017). "Mice that overexpressed IL-17, TNF-α and IL-1β in the lung developed highly progressive pulmonary fibrosis." (PMID 28466866, 2017). "MSC therapy inhibits the progression of BLM‐induced pulmonary fibrosis by altering proinflammatory cytokine tumor necrosis factor‐α and IL‐1β and by reducing the infiltration of inflammatory cells, such as neutrophils and lymphocytes, in a paracrine way." (PMID 28297588, 2017). "In conclusion, our study has demonstrated that AngII induction of mir-21 is a crucial factor that mediates pulmonary fibrosis by activating the NLRP3 inflammasome/IL-1β secretion axis via the Spry1/ERK/NF-κB pathway." (PMID 29084974, 2017). "Idiopathic pulmonary fibrosis is a progressive lung disease involving IL-1β–stimulated lung epithelial cells in which epithelial repair processes, lung inflammation, and fibroproliferation are triggered." (PMID 29254155, 2017). "The current results agreed with researchers who found increases in TNF, IL-1β, and IL-6 in bronchoalveolar lavage fluid in pulmonary fibrosis rat model." (PMID 28883083, 2017). "This clearly proposed that ATP released from bleomycin-injured lung cells constitutes a major endogenous danger signal that engages the P2X receptor/pannexin-1 axis, leading to IL-1β maturation and lung fibrosis." (PMID 27247426, 2016). "It has also been previously demonstrated that pulmonary fibrosis is closely associated with the activation of NLRP3-inflammasome pathway, production of IL-1β and TIMP-1." (PMID 27247426, 2016).
pulmonary fibrosis (continued). "Of interest, our longer term (21 day post exposure) aspiration study in mice did observe NLRP3 inflammasome activation (2.4 fold increase in BALF levels of IL-1β) and pulmonary fibrosis in response to La2O3 nanoparticles." (PMID 27527840, 2016). "Consistently with this finding, our studies showed that MyD88 and IL-1β were increased in pulmonary fibrosis and that inverse levels of MyD88 and IL-1β were observed after the overexpression of miR-489." (PMID 27506999, 2016). "Increased expression of TNF-α and IL-1β has been found in the lungs of patients and animal models of pulmonary fibrosis." (PMID 26977316, 2016). "In this context, a panel of pro-inflammatory cytokines including TNF-α, IL-1α, IL-1β, and IL-6 have been shown to be pro-fibrotic factors in both mouse and human lung fibrosis models." (PMID 27814727, 2016). "Released cathepsin B from lysosomes to the cytosol will activate NLRP3 inflammasomes to produce IL-1β, which initiate a cascade of events that culminate in pulmonary fibrosis." (PMID 28649460, 2016). "Our selection includes cytokines previously associated with the lung response to radiation in both mice and humans such as Il6 and Tnfα) as well as pulmonary fibrosis-promoting Il1β, Il13 and Il17) and anti-fibrotic mediators Il10 and Ifnγ." (PMID 25889053, 2015). "A number of inflammatory cytokines including TNFα and IL-1β are overexpressed in preclinical models of lung fibrosis and in lung tissue from IPF patients." (PMID 26231702, 2015). "A-MWCNTs delivered to the lungs of mice by OPA had reduced mRNA or protein levels of IL-1β, IL-6, OPN and TNF-α relative to U-MWCNT at 1 or 28 days post-exposure and A-MWCNTs caused less lung fibrosis in mice relative to U-MWCNTs." (PMID 25216247, 2014). "In a bleomycin-induced lung fibrosis murine model, ATP released from damaged lung cells leads to IL-1β maturation and lung fibrosis via P2X7R." (PMID 24533168, 2014). "In particular, IL-1β-induced and bleomycin-induced lung fibrosis seems to depend on the action of IL-17A, and in addition, IL-17A−/− mice are less susceptible to experimental skin fibrosis." (PMID 23834907, 2013). "IL-6, in addition to being a broad pro-inflammatory marker, is a target for IL-1β-induced lung fibrosis." (PMID 23741300, 2013). "Recent animal studies have identified the importance of P2X7 receptor and pannexin-1 complex in IL-1β maturation, inflammation and evolution to pulmonary fibrosis." (PMID 23634990, 2013). "IL-1β can induce lung fibrosis and release of a variety of chemokines, including monocyte chemotatic protein-1, MIP-1α." (PMID 24278171, 2013). "The activation of NLRP3 inflammosmes results in an inflammatory response mainly driven by the secretion of IL1β, a pro-fibrotic cytokine, playing an essential role in the pathogenesis of inflammation-induced pulmonary fibrosis." (PMID 23110140, 2012). "This suggested that Tregs modulated the Th17 differentiation in silica-induced lung fibrosis in an IL-1β dependent way." (PMID 22615967, 2012). "All these data suggested that IL-1β secretion increased in response to silica and Tregs depletion decreased the level of IL-1β in silica induced lung fibrosis." (PMID 22615967, 2012). "These macrophages produce chemokines (including KC, MIP-2) and pro-inflammatory cytokines (including IL-6 and IL-1β) that recruit other inflammatory cells to the lung, culminating in pulmonary fibrosis." (PMID 22708497, 2012). "While this study was being finalized, Wilson and colleagues published a study reporting a critical role for IL-17A in BLM- or IL-1β-induced lung fibrosis." (PMID 21858022, 2011). "Using the murine model of bleomycin (BLM)-induced lung fibrosis, we previously showed that inflammation and fibrosis were mediated through the pro-inflammatory and pro-fibrotic cytokine IL-1beta (IL-1β) and IL-1R1/MyD88 signaling in resident cells." (PMID 21858022, 2011).